NLRP3 (NLR family pyrin domain containing 3)
Diseases named in the same sentence as NLRP3 in open-access papers (continued):
Sharing a sentence is not in itself a finding about the gene and the disease.
liver fibrosis (continued). "Because previous studies have shown the importance of Nlrp3 and ASC in hepatic stellate cells for the development of liver fibrosis, future studies will determine the role of the Nlrp3 inflammasome in the specific cell types for the development of ALD." (PMID 24453428, 2013). "The activation of NLRP3 inflammasomes in liver stellate cells aggravates nonalcoholic steatohepatitis-induced liver fibrosis." (PMID 40225863, 2025). "KCs, induced by PRRs, NLRP3 in inflammatory vesicles, release various cytokines which trigger the classical TGF-β and PDGF pathways to promote the interaction between HSCs and KCs, further activating HSCs and facilitating the process of liver fibrosis." (PMID 40761743, 2025). "Berberine inhibits NLRP3 inflammasome activation and downstream signaling factor expression via the ROS/TXNIP pathway or NF-κB signaling pathway, ultimately inhibiting hepatocyte pyroptosis and attenuating NAFLD and liver fibrosis." (PMID 40667485, 2025). "In a thioacetamide-treated mouse model, the expression of liver fibrosis markers and inflammatory responses mediated by macrophages was suppressed after the inhibition of HMGB1, TLR4 and the assembly of NLRP3/ASC inflammasomes induced by LPS/ATP in mouse peritoneal macrophages." (PMID 40761743, 2025). "High IL-1β/IL-6 and NLRP3 levels drive liver fibrosis in experimental models of non-alcoholic fatty liver disease (NAFLD) mice." (PMID 40332584, 2025). "Therefore, decreasing expression level of IL-1β and NLRP3 and increasing values of NFS can be used as non-invasive methods to assess advanced hepatic fibrosis." (PMID 39179677, 2024). "Furthermore, NLRP3 ≤ 2.54 was able to significantly distinguish between early and severe post-MAFLD hepatic fibrosis with a sensitivity of 44.19% and a specificity of 100%." (PMID 39179677, 2024). "However, splenectomy can ameliorate liver fibrosis and cirrhosis by restoring gut barrier function and maintaining gut microbiota balance by inhibiting the TLR4/NLRP3 signaling pathway." (PMID 39635524, 2024). "NLRP3 activation up-regulates fibrotic markers in hepatic stellate cells and Nlrp3 knock-in mice demonstrate increased liver fibrosis and enhanced collagen production, even independent of the degree of inflammation." (PMID 38672492, 2024). "Deletion of Nlrp3 in myeloid-derived cells resulted in reduced activation of HSCs and liver fibrosis, whereas deletion of Nlrp3 in HSCs or hepatocytes did not confer protection." (PMID 38540172, 2024). "NLRP3 and GSDMD knockout mice manifest milder liver fibrosis phenotypes." (PMID 38380334, 2024). "In NLRP3-mutant mice, the inhibition of ASK1 alleviated liver fibrosis and inflammation; however, phase III trials of the ASK1 inhibitor selonsertib did not demonstrate benefits in patients with MASH or severe alcoholic hepatitis (AH) compared to standard treatment." (PMID 39770566, 2024). "NLRP3 > 1.33 had a sensitivity of 97.5, specificity of 99.07, PPV of 99.2, NPV of 97.2, and 98.3 accuracy with an AUC of 0.991 (p value < 0.001) as predictors of post-MAFLD hepatic fibrosis.." (PMID 39179677, 2024). "NLRP3 activation in HCC may be related with hepatocyte destruction and liver fibrosis, accelerating the course of the disease." (PMID 38780447, 2024). "Thus, the NLRP3 inflammasome induces hepatic stellate cell (HSC) activation and collagen deposition, leading to hepatic fibrosis, consistent with the results of the present study." (PMID 38547097, 2024). "RNA sequencing of livers from mice with CCl4-induced liver fibrosis revealed that the STING and NLRP3 inflammasome signaling pathways were activated during liver fibrosis, and the activation of these two pathways were also verified in human and mouse cirrhotic tissues." (PMID 38195584, 2024). "In NLRP3 overexpressing HCC mice, it was found that the mice had shorter survival time, poor growth, neutrophil infiltration and hepatic stellate cell activation, severe hepatitis response, and significant liver fibrosis." (PMID 37081882, 2023).
liver fibrosis (continued). "In studies based on LPS-induced neuroinflammation/microglia activation in mice and carbon tetrachloride-induced liver fibrosis in mice, chaihu saponin D suppressed inflammatory responses by regulating the NF-κB/TLR4 signaling pathway, and by inhibiting NLRP3 inflammatory vesicle expression." (PMID 38054830, 2023). "This further suggested that the Asp inhibited NF-κB/NLRP3 signaling pathway by upregulating the expression of NS3TP1, which might be the mechanism by which Asp regulated liver fibrosis, at least in part." (PMID 36983568, 2023). "In vitro experiments have shown that extracellular ATP can activate HSC NLRP3 via the purinoceptor P2X ligand-gated cation channel 7 (P2X7) and promote the release of fibrotic markers such as α-SMA and type I collagen leading to liver fibrosis." (PMID 37081882, 2023). "In NAFLD, inflammasomes, particularly NLRP3, exert a substantial impact on the progression of the liver disease, ranging from steatosis to nonalcoholic steatohepatitis (NASH) and subsequently to liver fibrosis, by orchestrating pyroptosis." (PMID 37685870, 2023). "We used a specific inhibitor of NLRP3, MCC950, to treat CCl4-induced liver fibrosis mouse models." (PMID 36429008, 2022). "Moreover, S1P/S1PR signaling has been shown to be involved in liver fibrogenesis by influencing the NLR family pyrin domain containing 3 (NLRP3) inflammasome, which is a critical mediator of inflammation-driven liver fibrosis." (PMID 36232681, 2022). "The NLRP3 inflammasome plays an important role in the innate immune response during the development of liver diseases such as non-alcoholic steatohepatitis (NASH), hepatitis, hepatic fibrosis, and liver cancer." (PMID 35138513, 2022). "Another study revealed that the continuous activation of NLRP3 in HSC can result in significant increase of α‐SMA positive cells, larger sirius red staining area, and exhibit severe liver fibrosis by using a model with selective expression of mutant hyperactive NLRP3 in HSC." (PMID 35415891, 2022). "Mechanically, NLRP3-mediated M1 macrophage polarization was blocked by the TGR5 signaling pathway, which further restored liver steatosis, inflammatory infiltration, and liver fibrosis." (PMID 35707547, 2022). "PA could also significantly up-regulate SOD and GSH-px levels (p<0.01), down-regulate IL-1β, IL-18, caspase-1, NLRP3, and TNF-α protein or gene expression in PBC mice (p<0.01) and inhibit liver fibrosis levels (p<0.01)." (PMID 35195182, 2022). "In conclusion, the current study suggests that S100A8 stimulates NLRP3 inflammasome-dependent pyroptosis in macrophages via activating TLR4/NF-κB signaling and inducing ROS abundance, which finally facilitates the progression of liver fibrosis." (PMID 36429008, 2022). "However, we agree with the points on the importance of NLRP3 activation in macrophages involved in the development of NAFLD and liver fibrosis, and we will continue to perform related studies in the future." (PMID 36558977, 2022). "Research indicates that the activation of NLRP3 inflammasome in HSCs can increase the number of α-SMA-positive cells, while positive α-SMA expression is the key marker of HSC activation, which is closely related to liver fibrosis progression." (PMID 35371052, 2022). "In the present study, we demonstrated that S100A8 as a crucial DAMP could stimulate NLRP3 inflammasome-dependent pyroptotic macrophage death by activating TLR4-dependent NF-κB and inducing ROS abundance, finally facilitating liver fibrosis progression." (PMID 36429008, 2022). "Moreover, activation of the NLRP3 pathway promotes hepatic stellate cell (HSC) activation, which is critical for the initiation and development of liver fibrosis." (PMID 32296329, 2020). "The regulation of the NLRP3 complex could become a new alternative to the treatment of NAFLD and liver fibrosis, especially in elderly people with severe liver damage." (PMID 32977490, 2020).
liver fibrosis (continued). "Unrepressed NLRP3 activation has been shown to result in shortened survival, severe liver inflammation, and hepatic stellate cell (HSC) activation, leading to collagen deposition and liver fibrosis." (PMID 33353156, 2020). "We used an NLRP3 inflammasome inhibitor, MCC950, to investigate whether it inhibited liver fibrosis, and explored the preliminary molecular mechanism." (PMID 30635040, 2019). "Our results showed a significant increase in NLRP3 but not of MyD88 at 24 h and 3 weeks and in pannexin-1 at 3 weeks in CCl4-induced liver fibrosis in mice." (PMID 27247426, 2016). "Mice lacking inflammasome components ASC and NLRP3 have reduced thioacetamide or carbon tetrachloride -induced liver fibrosis." (PMID 23409132, 2013). "Ursolic acid inhibits KC pyroptosis in liver fibrosis in vitro and in vivo by suppressing the protein expression of pyroptosis-related indicators (NLRP3, pro-caspase-1, cleaved caspase-1, GSDMD, GSDMD-N, and IL-1β) in the NOX2/NLRP3 inflammasome signaling pathway." (PMID 40667485, 2025). "At the same time NLRP3 > 1.33 significantly discriminating between post-NAFLD hepatic fibrosis and non-fibrotic liver in patients with different body mass index and different metabolic risk factors with a sensitivity of 97.5%, specificity of 99.07%, PPV of 99.2%, NPV of 100% and accuracy of 98.3%." (PMID 39179677, 2024). "In carbon tetrachloride (CCl4)-induced hepatic fibrosis rat models, SIRT1 overexpression attenuates the conversion of macrophages to the pro-inflammatory M1 type and inhibits the release of inflammatory cytokines via downregulation of the nuclear factor kappa B (NF-κB)/NLRP3 pathway." (PMID 38543036, 2024). "However, few fibrosis events were observed in the NLRP3−/− + CCl4 and NLRP3−/− + GCDCA groups, suggesting that the NLRP3 inflammasome pathway may be critically involved in the process of liver fibrosis driven by a diverse array of factors." (PMID 38172440, 2024). "By administering a specific dosage of FCD, the expression of inflammation-related genes such as NLRP3 and TNF-α was reduced to their usual levels, suggesting that FCD plays a role in impeding the conversion of stellate cells to fibroblasts and reducing liver fibrosis." (PMID 38790823, 2024). "Several lines of investigation indicate that the NLRP3 inflammasome activation is an important step that drives pro-fibrotic changes in tissue, and that this inflammatory complex could contribute significantly to both IPF and liver fibrosis." (PMID 37818376, 2023). "NLRP3 inflammasome may play a direct role in HSC activation and liver fibrosis." (PMID 37081882, 2023). "When NLRP3 or ARRB2 was successfully silenced, as detected using real-time qPCR and Western blot, we analyzed the mRNA and protein levels of genes related to inflammation and liver fibrosis, including IL-1β, IL-18, p-NF-κB, COL III, FN, and α-SMA in LX-2 cells." (PMID 36983568, 2023). "We found that genetic deletion of Nlrp3 or Casp1, or pharmacologic inhibition of Nlrp3 using an oral inhibitor (MCC950) did not ameliorate the development of any of the histological features of fibrosing steatohepatitis (hepatic fibrosis, inflammation, or steatosis) in HFHC-fed mice." (PMID 36641116, 2023). "BDL elicits a cholestatic injury and periportal biliary liver fibrosis, but this might be independent of NLRP3-independent mechanisms as a BDL-surgery increases liver fibrosis in the absence of caspase 1 in mice." (PMID 37492223, 2023). "Therefore, we hypothesized that the inhibition of the NLRP3 inflammasome could regulate HSC activation and prevent hepatic fibrosis from progressing." (PMID 36834849, 2023).
liver fibrosis (continued). "Previously, it was reported that upstream blockade of IL-1β maturation by NLRP3 inflammasome and caspase-1 inhibition reduced hepatic fibrosis, proving that lacking IL-1β in NASH may ameliorate pro-fibrotic events." (PMID 36611037, 2023). "Likewise, recent studies also show that X-box binding protein 1 (XBP1) regulates STING signaling and the subsequent NLRP3 activation during liver fibrosis, suggesting that macrophage self-mtDNA cytosolic leakage activates cGAS/STING/NLRP3 pathway providing a novel target against liver fibrosis." (PMID 36430874, 2022). "Till date, NLRP3 inflammasome is widely studied in liver diseases with its activity in liver diseases being comprehensively investigated, and numerous studies showing a key role of NLRP3 inflammasome in the pathogenesis of liver diseases, especially NAFLD, liver fibrosis, cirrhosis, and HCC." (PMID 32211410, 2020). "Other studies have found that casticin improves liver fibrosis by suppressing TGF-β and the Smad pathway, and it may also protect against the inflammatory response in LPS-induced acute lung injury in mice by inhibiting the NF-κB and NLRP3 pathways." (PMID 29962952, 2018). "Along these lines, a recent study using mice expressing a constitutively active form of NLRP3 under the control of the endogenous NLPR3 promoter, has shown that increased NLRP3 activity results in extensive liver inflammation, hepatocyte pyroptosis, and liver fibrosis." (PMID 28249038, 2017). "Paeoniflorin could reduce cholestatic inflammation and liver fibrosis in the PBC mouse model by eliminating mtROS through the SIRT1/forkhead box O1 (FOXO1)/superoxide dismutase 2 (SOD2) signaling pathway, and thereby alleviate mitochondrial damage and inhibit NLRP3 inflammasome activation." (PMID 36969233, 2023). "Similarly, in a study of a mouse model of liver fibrosis, LPS/ATP treatment increases the contents of cathepsin B and ROS and activates NLRP3 inflammasome, while LPS/ATP and cathepsin B inhibitors fails to increase levels of NLRP3 and IL-1β." (PMID 37370025, 2023). "Interestingly, MCD-induced NASH in NLRP3−/− mice showed that serum alanine transaminase (ALT), aspartate transaminase (AST), IL-1β, and IL-18 levels were lower than those in non-knockout mice and significantly reduced hepatocyte inflammation, hepatomegaly, and liver fibrosis." (PMID 36016562, 2022). "Finally, to verify the in vivo significance of our hypothesis, Casp-1, ASC, NLRP3, and AIM2 KO mice and WT mice, as control, were infected with B. abortus, and 4 weeks later, animals were sacrificed to determine the role of inflammasome in the liver fibrosis." (PMID 32038610, 2019). "In mice lacking NLRP3 or ASC, the development of liver fibrosis induced by CCl4 and TAA was significantly impaired and MSU-induced upregulation of collagen I and TGF-βcould not be observed in ASC−/− HSCs." (PMID 27322427, 2016). "In a CCl4 and TAA-induced in vivo liver fibrosis model, expression of TGF-β and collagen-1 was significantly reduced in mice lacking either NLRP3 or the adaptor molecule ASC." (PMID 27247426, 2016). "Furthermore, in the CCl4-induced liver fibrosis model, overexpression of NEK7 specific in hepatocytes delivered by AAV8-TBG vector still did not affect the levels of NLRP3 inflammasome activation in the livers, consistent with the findings in the CDAHFD model." (PMID 41315267, 2025). "The development of liver fibrosis induced by CCl4 and TAA was apparently delayed in mice lacking NLRP3 or ASC, and the upregulation of Collagen I and TGF-β induced by MSU could not be observed in ASC-/- HSCs." (PMID 30635040, 2019).
Stroke (207 papers, 2012 to 2026). Sudden impairment of blood flow to a part of the brain due to occlusion or rupture of an artery to the brain. "The inflammatory responses to brain damage in the etiology of neurodegenerative disease and stroke have been implicated to be mediated by the NLRP3 inflammasome and its activation/related products, TXNIP, ASC specks, caspase- 1, and IL- 1β." (PMID 40272769, 2025). "The cytosolic pattern recognition receptor NLRP3 recruits the adapter protein apoptosis-associated speck-like (ASC) pro-caspase- 1 in response to several stroke-induced stimuli." (PMID 40272769, 2025). "The Thioredoxin-interacting protein (TXNIP), an inherent regulator of the Thioredoxin (TRX) system, associates with the NLRP3 inflammasome following a stroke, instigating an inflammatory cascade." (PMID 38377025, 2024). "We focused on these two abundant inflammasome subtypes, because the NLRP3 inflammasome has previously been implicated in the development of atherosclerosis, whereas stroke leads to systemic AIM2 inflammasome activation." (PMID 39112714, 2024). "Recent studies have shown that NLRP3 inflammatory corpuscles are key pathogenic effectors that lead to stroke-induced destruction of the blood–brain barrier by activating the inflammatory signaling cascade leading to endothelial cell death in the brain." (PMID 37636861, 2023). "The use of both NLRP3 and Caspase-1-targeted inhibitors was effective in improving stroke symptoms, which was associated with inhibition of the pyroptosis pathway." (PMID 37165005, 2023). "Amelioration of neurovascular damage and improved outcome in NLRP3-deficient mice of post-stroke, rendering NLRP3 essential toward a worse outcome following stroke." (PMID 36138981, 2022). "To evaluate the relevance of NLRP3 inflammasome inhibition on microglial pyroptosis after stroke, we analyzed the expressions of proteins associated with pyroptosis in the peri-infarct areas following NLRP3 knockdown with AAV-based shRNA." (PMID 34630845, 2021). "In animal models of stroke, high NLRP3-inflammasome assembly and IL-1β expression occur, while NLRP3 deficiency improves neurovascular damage." (PMID 34257822, 2021). "In conclusion, our results establish the NLRP3 inflammasome as a critical pathogenic effector of stroke-induced BBB disruption by activating inflammatory signaling cascades and pyroptosis in brain EC." (PMID 34930895, 2021). "Caspase-1 activity, IL-1β, TNF-α, and NLRP3 have been demonstrated to be associated with modulation of apoptosis after stroke, causing activation of caspase-dependent pathways of cell death." (PMID 34257822, 2021). "Inhibition of ERS-induced caspase-12 activation potentially decreases cerebral damage in stroke and thereby damage-associated molecular pattern-induced NLRP3 inflammasome activation." (PMID 32788872, 2020). "al data demonstrating NLRP3 deficiency ameliorated ischemic injury in cellular and animal models of stroke." (PMID 29654318, 2018). "Our recent study indicated that genetic or pharmacological ablation of the thioredoxin interacting protein (TXNIP) is associated with suppression of NLRP3 inflammasome and attenuation of stroke outcome." (PMID 29654318, 2018). "Stroke-associated inflammation was attenuated, evidenced by reduced Tnf, Nlrp3 and Aif1 expression." (PMID 42229070, 2026). "Furthermore, abnormal activation of NLRP3 is associated with pathological conditions such as stroke, trauma, and aging, where neuroinflammation further exacerbates disease progression." (PMID 40075143, 2025). "This includes expanding the use of genetic instruments and Mendelian randomization to test whether specific inflammatory pathways (e.g., IL‐6 signaling, NLRP3 inflammasome activity) are causally linked to stroke risk." (PMID 41456955, 2025).